USP10 (ubiquitin specific peptidase 10)
Diseases named in the same sentence as USP10 in open-access papers (continued):
Sharing a sentence is not in itself a finding about the gene and the disease.
ovarian carcinoma (13 papers, 2020 to 2023). A malignant neoplasm originating from the surface ovarian epithelium. "By contrast, in some datasets, lower USP10 expression was observed for brain and CNS cancer, bladder cancer, kidney cancer, ovarian cancer, and sarcoma." (PMID 35433424, 2022). "Based on clinical samples and bioinformatic analyses, high USP10 expression was observed in most cancer tissues except for ovarian cancer." (PMID 35433424, 2022). "Downregulated USP10 alone or combination of USP10/p14ARF are robust indicators of poor prognosis in ovarian cancer patients." (PMID 34412625, 2021). "Additionally, decreased expression of USP10 or combined USP10/p14ARF is a strong indicator of poor prognosis in patients with ovarian cancer." (PMID 36949071, 2023). "Furthermore, survival analysis found that low USP10 expression predicted poor prognosis in patients with ovarian cancer." (PMID 35433424, 2022). "However, low expression of USP10 predicts a poor prognosis in patients with ovary cancer." (PMID 35433424, 2022). "Overexpression of both USP10 and HDAC6 has been observed in lung and ovarian cancer." (PMID 32382008, 2020). "To test this hypothesis, we depleted USP10 in seven NSCLC and two ovarian cancer cell lines and treated them with either a vehicle or cisplatin to examine cell viability by MTT assays." (PMID 32382008, 2020). "Additionally, the dual loss of USP10 and ARF expression is frequently observed in small intestinal adenocarcinoma and ovarian cancer patients, thus implying that low combined USP10/ARF expression is a prognostic marker of small intestinal adenocarcinoma and ovarian cancer." (PMID 32759846, 2020). "The results showed that the mRNA levels of USP10 were significantly overexpressed (p < 0.01) in three histological subtypes of NSCLC—lung adenocarcinoma, squamous cell lung carcinoma, and large cell lung carcinoma —and ovarian cancer when compared with normal tissues." (PMID 32382008, 2020).
acute myeloid leukemia (9 papers, 2018 to 2025). Acute myeloid leukemia (AML) is a group of neoplasms arising from precursor cells committed to the myeloid cell-line differentiation. "USP10 acts as a cancer-promoting factor in liver cancer and acute myeloid leukemia through stabilization of YAP and FLT3." (PMID 36526897, 2023). "For example, USP10 is the important deubiquitinase required to stabilize oncogenic forms of the kinase FLT3, a critical therapeutic target in acute myeloid leukemia (AML)." (PMID 37072811, 2023). "The results showed that USP10 mRNA was highly expressed in most tumor types, except for bladder cancer (BLCA), brain and central nervous system cancer, OV, sarcoma (SARC), acute myeloid leukemia (AML), and THYM." (PMID 35433424, 2022). "However, in acute myeloid leukemia (AML) patients with activating mutations in FMS‐like tyrosine kinase 3 (FLT3), USP10 deubiquitinates and stabilizes FLT3 by removing the proteolytic polyubiquitin chains and preventing FLT3 degradation, to aggravate tumor progress." (PMID 31721429, 2020). "However, significantly lower USP10 expression was observed in acute myeloid leukemia (LAML) and thymoma (THYM) compared with that in adjacent normal tissues." (PMID 35433424, 2022).
liver cancer (9 papers, 2021 to 2024). An epithelial or non-epithelial malignant neoplasm that arises from the liver. "Taken together, this study revealed a role of USP10 in liver cancer by promoting Yap/Taz stability and suggested a potential new strategy for therapeutical intervention." (PMID 33869224, 2021). "Additionally, USP10 can also stabilize Smad4 by ubiquitinating it, which contributes to liver cancer metastasis." (PMID 37143582, 2023). "USP10 stabilizes Smad4 by ubiquitinating it, activates TGF‐β signaling, and promotes liver cancer metastasis." (PMID 37143582, 2023). "USP22, USP14, USP10, USP13, USP7, USP2, and USP8, liver cancer-related DUBs, have also been reported to have related small molecule inhibitors, but the research and development are not mature enough." (PMID 35875077, 2022). "Previous studies have reported that USP10 promotes cisplatin resistance by deubiquitinating HDAC6 in non-small cell lung cancer, and promotes tumor growth and proliferation by deubiquitinating TAZ/YAP in liver cancer." (PMID 38321024, 2024). "In addition, USP10 is also a tumor-related factor in human lung cancer, CRC, liver cancer, etc.." (PMID 35875077, 2022).
non-small cell lung carcinoma (9 papers, 2020 to 2025). A group of at least three distinct histological types of lung cancer, including non-small cell squamous cell carcinoma, adenocarcinoma, and large cell carcinoma. "We also found an increase in caspases-3 and -7 activity, which is in agreement with the findings reported on the increased apoptosis in non-small-cell lung carcinoma cells, via a direct interaction with ubiquitin-specific protease 10 (USP10)." (PMID 32659970, 2020). "Notably, other USP family members—including USP22, USP10, and USP32—have been associated with adverse prognosis in various malignancies, including pancreatic ductal adenocarcinoma, non-small cell lung cancer." (PMID 40926837, 2025).
renal cell carcinoma (9 papers, 2014 to 2025). "Previous studies using RCC (renal-cell carcinoma) tissue microarrays indicated that USP10 expression was reduced in RCC samples compared with normal renal tissues." (PMID 35627217, 2022).
esophageal squamous cell carcinoma (8 papers, 2023 to 2025). Esophageal squamous cell carcinoma (ESCC) is a type of esophageal carcinoma (EC) that can affect any part of the esophagus, but is usually located in the upper or middle third. "According to another study, USP10 functions as a scaffold protein in esophageal squamous cell carcinoma, increasing DNA repair activity and decreasing the lethality of ionizing radiation." (PMID 39267084, 2024). "The oncogene ANLN could be targeted and enhanced by USP10, leading to inferior prognosis for patients with esophageal squamous cell carcinoma." (PMID 40672387, 2025). "In esophageal squamous cell carcinoma (ESCC), USP10 deubiquitinates MOF and maintains its stability by interacting with it." (PMID 39223632, 2024). "Here, we reveal ANLN plays a crucial role in cell division of esophageal squamous cell carcinoma (ESCC) and identify USP10 as a novel DUB for ANLN." (PMID 36526897, 2023).
Hepatic steatosis (8 papers, 2020 to 2024). Steatosis is a term used to denote lipid accumulation within hepatocytes. "SIRT6 overexpression markedly ameliorated the effects of USP10 deficiency on hepatic steatosis, insulin resistance, and inflammation." (PMID 33133065, 2020). "Besides, USP10 improves metabolic dysfunction associated with obesity by regulating liver steatosis, inflammation, and insulin resistance." (PMID 38322269, 2024). "SIRT6 overexpression can improve hepatic steatosis, insulin resistance, and inflammation, which regulates hepatic steatosis by interacting with USP10 and inhibiting SIRT6 ubiquitin and degradation." (PMID 36008973, 2022). "For example, USP10 expression is decreased and upregulated in hepatic steatosis models to inhibit hepatic steatosis, insulin resistance, and inflammation." (PMID 34412625, 2021). "In the NFALD model, USP10 regulates hepatic steatosis by interacting with SIRT6 and inhibiting its ubiquitination and degradation." (PMID 33133065, 2020). "USP10 inhibits hepatic steatosis, insulin resistance, and inflammation through Sirt6." (PMID 39430239, 2024). "LncRNA Mirt2 upregulates USP10 to repress hepatic steatosis by targeting miR-34a-5p." (PMID 35322757, 2022). "USP10 interacts with SIRT6 to inhibit its ubiquitination and degradation, thereby preventing fatty liver and cardiac hypertrophy." (PMID 34412625, 2021). "Furthermore, USP10 plays a role in attenuating hepatic steatosis in nonalcoholic steatohepatitis (NASH) through the promotion of autophagy, which alleviates hepatic steatosis, inflammation, and fibrosis." (PMID 38322269, 2024).
chronic myeloid leukemia (7 papers, 2019 to 2026). "Indeed, USP10 can recognize and remove Lys63-linked ubiquitin chains from Bcr-Abl, leading to positive activities in chronic myeloid leukemia cells." (PMID 35874839, 2022). "In chronic myeloid leukemia cells, USP10 amplified the activation of Bcr-Abl by mediating the deubiquitination of SKP2 and stabilization." (PMID 37915040, 2023). "Moreover, it has been shown that the inhibition of the deubiquitinating enzyme USP10 inhibits proliferation in chronic myeloid leukemia (CML) cells, both in imatinib-sensitive and imatinib-resistance cells." (PMID 39272922, 2024).
Insulin resistance (7 papers, 2020 to 2024). Increased resistance towards insulin, that is, diminished effectiveness of insulin in reducing blood glucose levels. "The beneficial effects of USP10 on insulin sensitivity were abolished by Sirt6 deficiency, and overexpression of Sirt6 strongly abrogated the insulin resistance observed in Usp10KO mice." (PMID 36834633, 2023). "Furthermore, ubiquitin-specific peptidase 10 (USP10) interacts with SIRT6 and inhibits its ubiquitination and degradation, while Sirt6 overexpression attenuates USP10 deficiency-potentiated hepatic insulin resistance, steatosis, and inflammation." (PMID 39372420, 2024). "In nonalcoholic fatty liver disease, decreased expression of miR-34a-5p/USP10 was involved in hepatic insulin resistance and steatosis in obese mice." (PMID 37915040, 2023). "Knockout and overexpression of Usp10 in the liver promoted or attenuated high fat diet–induced insulin resistance, respectively." (PMID 36834633, 2023). "Similarly, Usp10 overexpression dampened insulin resistance in ob/ob mice." (PMID 36834633, 2023). "Ubiquitin-specific peptidase 10 (USP10) inhibits SIRT6 ubiquitination and degradation, reducing liver fat deposition, insulin resistance, and inflammation." (PMID 37876546, 2023).
melanoma (7 papers, 2011 to 2025). A malignant, usually aggressive tumor composed of atypical, neoplastic melanocytes. "Knock‐down of USP10/USP13 increased cellular apoptotic rate approximately 2‐3 folds in A375 or Sk‐Mel‐28 human melanoma cells." (PMID 32129945, 2020). "In the initial screening of melanoma samples, five genes (USP10, USP11, USP22, USP48 and COPS5) were significantly overexpressed, compared with benign nevi." (PMID 21283576, 2011). "In addition, Spain-1, an inhibitor of USP10, inhibits melanoma growth and improves the anticancer effect of cisplatin by inhibiting USP10 activity." (PMID 35627217, 2022). "In the present study, we discovered the high expression levels of USP10 and USP13 in malignant melanoma tissues and explored the function and underlying mechanisms of the anti‐melanoma effects of the USP10/USP13 inhibitor spautin‐1 through inducing the ROS‐mediated DNA damage." (PMID 32129945, 2020). "We have checked the expression of USP10 and USP13 in different melanoma cell lines and human skin keratinocytes cell line (HaCaT)." (PMID 32129945, 2020). "We found that there were higher USP10 and USP13 expression in melanoma cell lines compared with control cells." (PMID 32129945, 2020). "To assess the role of USP10 and USP13 in melanoma progression, we applied melanoma tissue microarray and immunohistochemistry to detect their expression." (PMID 32129945, 2020). "USP10 and USP13 were highly expressed in malignant melanoma specimens compared to the naevus tissue." (PMID 32129945, 2020). "In this study, we employed a potent USP10/13 deubiquitinating activity antagonist, spautin‐1, to investigate the effect of targeting USP10/USP13 as an anti‐melanoma treatment and found that melanoma cell proliferation was significantly suppressed by spautin‐1‐induced ROS‐mediated DNA damage." (PMID 32129945, 2020). "All the results suggested that USP10 and USP13 might play detrimental roles in melanoma." (PMID 32129945, 2020). "Spautin‐1 has been reported as a USP10 and USP13 antagonist, and we demonstrated that spautin‐1 has potent anti‐tumour effects as reflected by MTS and the colony formation assays in various melanoma cell lines without cytotoxic effects in HaCaT and JB6 cell lines." (PMID 32129945, 2020).
Parkinson disease (6 papers, 2018 to 2025). A progressive degenerative disorder of the central nervous system characterized by loss of dopamine producing neurons in the substantia nigra and the presence of Lewy bodies in the substantia nigra and locus coeruleus. "In Parkinson’s disease brains, USP10 colocalized with α-synuclein in the disease-linked aggresome-like inclusion-bodies called Lewy bodies, suggesting that USP10 limits α-synuclein-induced neurotoxicity by promoting Lewy body formation." (PMID 33277473, 2020). "USP10 induced the formation of aggresomes containing α-synuclein, a pathogenic protein in Parkinson’s disease, in cultured cells." (PMID 33277473, 2020). "USP10 induced aggresomes containing α-synuclein, a pathogenic protein in Parkinson disease, in cultured cells." (PMID 30469013, 2018). "In Parkinson disease brains, USP10 was colocalized with α-synuclein in the disease-linked aggresome-like inclusion Lewy bodies, suggesting that USP10 inhibits α-synuclein-induced neurotoxicity by promoting Lewy body formation." (PMID 30469013, 2018). "Previous studies established the cross-talk between USP10 and fibrosis in multiple tissues, which are down-regulated in cancers, Parkinson disease (PD), and keloids, and specifically render the heart susceptible to hypertrophy injury." (PMID 34957094, 2021). "We have discussed the importance of USP10 in different cancers, in AD, Parkinson’s disease, and cystic fibrosis." (PMID 33277473, 2020). "Indeed, G3BP1 was recently described to promote proteasomal function and inhibit accumulation of ubiquitinated protein aggregates associated with Parkinson’s (α-synuclein) and Cystic Fibrosis (CFTR-ΔF508), which were induced by p62 and USP10." (PMID 32992901, 2020).
thyroid cancer (6 papers, 2020 to 2025). "Recently, Ubiquitin-specific peptidase 10 (USP10) was found to be associated with poor prognosis in patients with thyroid cancer (THCA)." (PMID 40959280, 2025). "To study the underlying mechanism by which USP10 could affect the biological characteristics of DOX-resistant FTC133-DOX thyroid cancer cells, we investigated PTEN/PI3K/AKT/ABCG2 signaling axis." (PMID 37919637, 2023). "This study found that USP10 affects the drug resistance of thyroid cancer cells by regulating the PTEN/PI3K/AKT pathway." (PMID 37919637, 2023). "In order to elevate the role of USP10 in sensitivity to DOX of thyroid cancer cells and based on the experimental results of its abnormally low expression, pcDNA-USP10 was transfected into FTC133 and FTC133-DOX cells to overexpress expression of USP10." (PMID 37919637, 2023). "Our results also indicated that overexpression of USP10 promoted apoptosis of DOX resistance thyroid cancer cells." (PMID 37919637, 2023). "In our study, we found that the expression of USP10 in DOX-resistant thyroid cancer cells is lower than that in their parental cells." (PMID 37919637, 2023). "At the same time, our study also showed that overexpression of USP10 inhibited the malignant biological behavior of DOX-resistant thyroid cancer cells by inhibiting the expression of ABCG2 by regulating the PTEN/PI3K/AKT pathway." (PMID 37919637, 2023). "This strongly suggests that USP10 plays a critical role in DOX resistance to the thyroid cancer cell." (PMID 37919637, 2023). "Our study also showed that overexpression of USP10 inhibited the malignant biological behavior of DOX-resistant thyroid cancer cells, while concomitant overexpression of ABCG2 reversed this inhibition caused by USP10." (PMID 37919637, 2023). "At the same time, our study also showed that overexpression of USP10 inhibited the malignant biological behavior of DOX-resistant thyroid cancer cells, while concomitant overexpression of ABCG2 reversed this inhibition caused by USP10." (PMID 37919637, 2023). "Out of 28 protein-coding, five genes; TERT, FLT4, DUSP6, USP10 and POMC have already been implicated in thyroid cancer." (PMID 32324757, 2020). "Furthermore, USP10 targeted ABCG2 to inhibit all these malignant processes, therefore, either increasing USP10 expression or inhibiting ABCG2 could be used as novel targets for treating DOX-resistant thyroid cancer." (PMID 37919637, 2023). "Moreover, overexpression of USP10 promotes the apoptosis of DOX-resistant thyroid cancer cells." (PMID 37919637, 2023). "Recent research indicates that ubiquitin-specific peptidase 10 (USP10) facilitates the proliferation and metastasis of tumor cells by inhibiting ferroptosis in thyroid cancer cells." (PMID 39917169, 2025). "Mechanistically, overexpressing USP10 inhibits the invasion, migration and EMT of thyroid cancer cells by regulating the expression of ABCG2 and mediating PTEN/PI3K/AKT signaling pathway." (PMID 37919637, 2023). "In this study, we found that the expression of USP10 was lower in thyroid cancer cells than that in normal thyroid cells, and it was lower in DOX resistance thyroid cancer cells than that in parental thyroid cancer cells." (PMID 37919637, 2023). "In this study, we also found that overexpression of USP10 inhibited invasion, migration, and EMT properties of DOX-resistant thyroid cancer cells." (PMID 37919637, 2023). "However, it is not known by which mechanism USP10 mediates these processes, especially in the case of thyroid cancer." (PMID 37919637, 2023).